KIAA1549L (KIAA1549 like)
Synonyms: C11orf41; C11orf69; G2; MGC34830
Tractability: Antibody: UniProt predicts a signal peptide or a membrane-spanning region. PROTAC: ubiquitination databases record sites on it.
Gene: Protein-coding gene on chromosome 11 (33,376,108 to 33,674,102, forward strand). Ensembl gene ENSG00000110427.
Subcellular location: Membrane
Subcellular location (Human Protein Atlas): Nucleoplasm; Vesicles
Genetic constraint (gnomAD): Loss-of-function variants: 82 observed, 138.67 expected, observed/expected ratio (o/e) 0.59, 90% interval 0.49 to 0.71. The upper end of that interval is the gene's LOEUF score, 0.71, which puts it in group 2 of 6, group 1 being the genes least tolerant of losing a copy. Missense variants: 2,078 observed, 2,359.8 expected, observed/expected ratio (o/e) 0.88, 90% interval 0.85 to 0.91. Synonymous variants: 876 observed, 946.13 expected, observed/expected ratio (o/e) 0.93, 90% interval 0.88 to 0.98.
Homologues: Orthologues: macaque KIAA1549L (96% identical), chimpanzee KIAA1549L (85% identical), pig KIAA1549L (76% identical), dog KIAA1549L (74% identical), rat D430041D05Rikl (74% identical), mouse D430041D05Rik (72% identical), rabbit KIAA1549L (67% identical), guinea pig KIAA1549L (56% identical), zebrafish kiaa1549la (24% identical), zebrafish kiaa1549lb (3% identical). Paralogues in human: KIAA1549 (19% identical).
Diseases named in the same sentence as KIAA1549L in open-access papers:
KIAA1549L is named in the same sentence as 8 diseases in open-access papers, as found by Europe PMC text mining. Sharing a sentence is not in itself a finding about the gene and the disease. The quoted sentences say what the papers report.
colorectal cancer (1 paper, 2019). A primary or metastatic malignant neoplasm that affects the colon or rectum. "By evaluating leukocyte DNA methylation patterns to identify potential biomarkers for the early detection of colorectal cancer, two differentially methylated CpG sites located in the promoter region of KIAA1549L were identified." (PMID 31513639, 2019).
KIAA1549L also shares sentences with these, for which no sentence is quoted: acute leukemia (2 papers); acute lymphoblastic leukemia (1); cancer (1); cardiovascular diseases (1); diabetes (1); ovarian carcinoma (1); tumor (1).